INS (insulin)
Diseases named in the same sentence as INS in open-access papers (continued):
Sharing a sentence is not in itself a finding about the gene and the disease.
diabetes (continued). "Studies conducted by Powrie and co-authors determined the effects of three days oral CQ administration on FBG and fasting plasma insulin among patients with non-insulin-dependent diabetes mellitus (NIDDM) (n=10; aged 43 - 61 years)." (PMID 34104100, 2021). "Since its discovery, the treatment of diabetes using insulin, derivatives of insulin, and other peptides has and continues to evolve." (PMID 33868177, 2021). "In humans, reduced LysoPC(18:2) levels were found in insulin-resistant individuals and appeared years ahead of diagnosis for Type 2 diabetes mellitus (T2D)." (PMID 34838065, 2021). "As well, ectopic expression of the TFs PDX1 and MAFA in human α-cells efficiently converts them into insulin-secreting cells that lead to diabetes reversal when transplanted into diabetic mice." (PMID 34340653, 2021). "Type 1 diabetic mellitus (T1DM) patients and approximately one-third of those with type 2 diabetes mellitus (T2DM) require exogenous insulin treatment." (PMID 34888280, 2021). "One of the most feared complications of diabetes treatment is hypoglycemia, which commonly occurs in clinical practice as approximately 90% of all patients who receive insulin have experienced hypoglycemic episodes." (PMID 34690922, 2021). "Focusing on the relationship of vitamin D with diabetes, it should be mentioned that this compound activates pancreatic beta-cells and regulates calcium hemostasis which has a positive effect on insulin secretion and sensitivity." (PMID 33801468, 2021). "In this study, we investigated the role of MSC-derived exosomes in pancreatic regeneration and insulin secretion in mice with streptozotocin-induced diabetes." (PMID 34926699, 2021). "In previous studies, diabetes treated with insulin was a self-reported parameter which is subject to potential recall bias, however, in our study, treatment with insulin was based on objective criteria, ICD-10 codes." (PMID 34521935, 2021). "Distribution of nursing procedures according to the nomenclature of health insurance procedures and according to the insulin therapy of patients with diabetes." (PMID 34917037, 2021). "Several participants reported to have limited knowledge regarding treatment of diabetes, especially knowledge about insulin and other antidiabetic drugs." (PMID 33570292, 2021). "The coexistence of T1DM and other autoimmune endocrinopathies impairs glucose metabolism, interferes with effective insulin therapy and deteriorates diabetes control." (PMID 33099763, 2021). "In contrast, genetic deletion of Ins1 or replacement of murine Ins1 with human insulin gene (INS) in NOD mice provides significant protection from diabetes." (PMID 33841427, 2021). "Other Key factor determinants for fractures in diabetic patients: insulin status and glucose levels affect bone vasculature in diabetes and muscle contribution to skeletal impairment in diabetes." (PMID 33850676, 2021). "We examined the effect of CR on whole-body glucose tolerance and fasting blood insulin concentrations in the late stage of diabetes." (PMID 33916828, 2021). "Recently, insulin treatment has been found to be associated with increased mortality and other adverse outcomes in patients with coronavirus disease 2019 (COVID-19) and diabetes, but the results remain unclear and controversial, therefore, we conducted this meta-analysis." (PMID 34367067, 2021). "We found that the first PC was highly correlated (R > 0.5) with diabetes markers such as insulin, LPIR, HOMA IR, and cardiovascular diseases markers such as triglycerides, and LDL, and anti-correlated (R < −0.5) with HDL and Adiponectin serum." (PMID 34117230, 2021). "Insulin and/or metformin were needed to control diabetes in 11.7% of patients, while in the remaining the disease was controlled solely through diet and exercise modification." (PMID 33997597, 2021).
diabetes (continued). "Our case report favors an insulin-resistance mechanism to explain hyperglycemia, with an increase in fasting C-peptide concentration and an insulin dose of up to 3.9 units/kg required to control diabetes." (PMID 34281618, 2021). "Insulin requirements were similar in patients with COVID‐19 and non‐COVID‐19 viral pneumonitis after adjustment for pre‐existing diabetes and severity of respiratory failure." (PMID 34268452, 2021). "Distribution of dentist consultations according to the regions of the territory and according to the insulin therapy of patients with diabetes." (PMID 34917037, 2021). "The majority of studies described a consistently positive association with different outcomes of interest related to DF for gender, peripheral neuropathy, retinopathy, nephropathy, poor glycaemic control, insulin use, duration of diabetes, smoking and height." (PMID 33532615, 2021). "Cav1 has exerted its effect on insulin signaling and lipid metabolism within the liver, adipose tissues, and skeletal muscles to influence diabetes development." (PMID 34394002, 2021). "Diabetes mellitus (DM) is a chronic metabolic disorder characterized by defective insulin secretion and reduced tissue sensitivity to insulin, leading to hyperglycemia." (PMID 34063950, 2021). "This allowed the present analysis to focus on a previously unexplored aspect of diabetes therapy – insulin discontinuation by healthcare providers." (PMID 33402226, 2021). "Diabetes mellitus is a group of metabolic diseases characterized by hyperglycaemia resulting from defects in insulin secretion, insulin action or both." (PMID 33676486, 2021). "Liver plays a major role in maintaining the balance of glucose homeostasis; however, in diabetes, the ability of insulin to trigger downstream metabolic actions is impaired, leading to alterations in the hepatic metabolism." (PMID 34208379, 2021). "Of interest is that insulin also directly stimulates glucose oxidation via enhancing mitochondrial Akt activity, and this effect is likely to also be attenuated in diabetes." (PMID 34831481, 2021). "Among all participants at baseline, 72.3% (261 of 361) were receiving insulin and 39.9% (144 of 361) were using an oral diabetes medication." (PMID 34028550, 2021). "Although many diabetes technologies, such as insulin pumps and continuous glucose monitors, have been established, the data from these devices are rarely assessed." (PMID 33571104, 2021). "MCTs are involved in maintaining interstitial fluids' pH and regulating insulin's binding affinity to its receptor, which is a potential mechanism for the onset of diabetes." (PMID 34257700, 2021). "The other respondents, who had never experienced a hypoglycaemic event, more often had a diabetes duration less than 10 years, had less diabetes related complications and used insulin less often compared to those with hypoglycaemic events." (PMID 34126938, 2021). "Five years after diagnosis, changes in self-reported habitual PA differently associated with improved physical performance in both diabetes groups, but with lower BW, FLI as well as waist circumference and a trend for higher insulin sensitivity only in T2D." (PMID 34659107, 2021). "It has been reported that UCN3 regulates insulin secretion and is dysregulated with increasing severity of obesity and diabetes." (PMID 34341463, 2021). "In fact, the intravenous (IV) infusion of insulin during euglycemia has been shown to lower glucagon levels in dogs, healthy humans, and patients with diabetes." (PMID 34003799, 2021). "Different alternatives exist for the treatment of diabetes, such as daily insulin application and glucose monitoring, diet changes, use of therapeutic drugs like N-acetylcysteine (NAC), and regular physical activity." (PMID 34099835, 2021).
diabetes (continued). "In clinical, diabetic retinopathy occurs both in type 1 diabetes mellitus (T1DM) featured with severe insulin deficiency and type 2 diabetes mellitus (T2DM) featured with insulin resistance and/or impaired insulin secretion." (PMID 34725563, 2021). "Here, we compare two different diabetes models: insulin-dependent (STZ-induced T1DM-like phenotype) and insulin-independent diabetes mellitus (db/db mouse model for T2DM)." (PMID 35052710, 2021). "Within this, it is important that healthcare professionals discuss treatment options available to patients with diabetes requiring insulin when reviewing different management approaches accessible and available within their healthcare systems." (PMID 35095504, 2021). "Intensive research is being carried out on artificial intelligence methods to help people with diabetes to optimize the way in which they use insulin, carbohydrate intakes, or physical activity." (PMID 34450712, 2021). "Diabetes Mellitus (DM) is a metabolic disorder characterised by persistent high blood glucose levels (hyperglycaemia), and inadequate insulin production or insulin dysfunctionality." (PMID 33499073, 2021). "Fast-acting glucagon (nasal administration and injected solutions) appears to represent a major breakthrough in the treatment of severe hypoglycemia in insulin-treated patients with diabetes, both adults and children." (PMID 34638984, 2021). "In fact, even insulin secretagogues, including sulfonylureas and glinides, ameliorate or relieve insulin resistance in patients with diabetes." (PMID 34556670, 2021). "Their median {IQR} diabetes duration was 8.0 {2.5–15.4} years, their median HbA1c 6.8 {6.2–7.7}% (51 {44–61} mmol/mol) and 15.7 % were insulin-treated." (PMID 34640520, 2021). "It was identified as a protective factor for diabetes mellitus that reduces immune cell infiltration, increases the number of insulin secretion islet β-cell, and reduces apoptosis pancreas islet." (PMID 33728329, 2021). "Abnormal metabolism of glucose in diabetes reduces insulin sensitivity and induces postprandial hyperglycemia contractile activity in the skeletal muscle." (PMID 33628395, 2021). "This article shows the achievements gained by a long exploration with the islets of Langerhans, during which we further clarified the physiology of insulin production and the pathogenesis of diabetes and its complications." (PMID 34629354, 2021). "To date, the main focus of research has been to investigate the role of insulin in the onset and progression of pathological conditions and chronic diseases, such as diabetes." (PMID 34203830, 2021). "Insulin is a scarce commodity, with global demands projected to rise due to increasing prevalence of diabetes." (PMID 34336550, 2021). "The intraperitoneal route of administration accounts for less than 1% of insulin treatment regimes in patients with diabetes mellitus type 1 (DM1)." (PMID 33848314, 2021). "80.5% of people with a prior diagnosis of diabetes reported taking oral medication for diabetes and over 50% reported taking insulin." (PMID 34294059, 2021). "Eight of these children had to continue insulin after they reached adult age (i.e., 18 years), which reflects both the severity of their diabetes and the difficulty of managing these patients with oral antidiabetic drugs alone." (PMID 34830599, 2021). "Type 2 diabetes mellitus (T2DM) is a major metabolic disease that is characterized by sustained high levels of blood glucose which result from defective secretion of insulin, ineffective insulin action, or both." (PMID 33750352, 2021). "We investigated the associations of these metabolites with incident diabetes and with early markers of diabetes, including fasting plasma insulin and glucose levels and the Gutt insulin sensitivity index (ISI), a measure of insulin sensitivity." (PMID 34448864, 2021).
diabetes (continued). "The relationship between vitamin D (VitD) and insulin sensitivity and secretion in type 2 diabetes mellitus (T2D) has been shown to be different amongst different ethnic populations." (PMID 34380489, 2021). "Our study shed new light on the clarification of the revelation of insulin balls and the development of the insulin analogs for diabetes therapy." (PMID 33767265, 2021). "The potential of stem cell‐derived insulin‐producing cells for the treatment of diabetes has been demonstrated using rodent models." (PMID 34387389, 2021). "At higher glucose concentrations, the diabetes model on chip showed faster saturation of insulin levels." (PMID 34680532, 2021). "Diabetes mellitus is a metabolic disorder characterized by chronic hyperglycemia resulting from defects in insulin secretion, insulin action, or both." (PMID 34003397, 2021). "As expected, the mean diabetes duration, daily insulin dose, HbA1c, IDDA1c, estimated HbA1c levels were significantly lower in the PRP group compared with the non-PRP group." (PMID 33485357, 2021). "Insulin (8%), continuous glucose monitors (6%) and fast‐acting carbohydrates (6%) were the diabetes‐related supplies most difficult to access due to the COVID‐19 pandemic so far." (PMID 33532617, 2021). "Diabetes mellitus is a group of metabolic diseases characterized by hyperglycemia due to defects in insulin production and/or insulin action together with impaired carbohydrates, lipids, and protein metabolism." (PMID 34480074, 2021). "The identical pattern was typical for both untreated and treated diabetes, and it only changed in the subpopulation having insulin treatment, where the number of MO health limitations exceeded that in the AD dimension." (PMID 34587218, 2021). "Noteworthy, β-like cells differentiated from WFS1-corrected hiPSCs showed robust and dynamic insulin secretion in response to glucose, and reversed streptozocin-induced diabetes when transplanted into mice." (PMID 34295307, 2021). "The development of diabetes indicates a mismatch between an increased insulin demand secondary to insulin resistance and insufficient islet β cell insulin secretion." (PMID 34108935, 2021). "Lipids are the major source of energy metabolism and are independent predictors for impairment of insulin actions and progression to diabetes." (PMID 35127558, 2021). "Insulin was first discovered 100 years ago and remains a necessary treatment for many people with diabetes." (PMID 34636912, 2021). "One meta-analysis has shown that short term resveratrol supplementation reduces insulin resistance, insulin concentration and fasting glucose in patients with diabetes." (PMID 34064568, 2021). "Diets rich in conjugated linoleic acid, have been shown to decrease inflammation, and consequently improve the markers of metabolic traits such as insulin sensitivity and neuropathy in diabetes." (PMID 33933074, 2021). "A high proportion of these patients required insulin infusion warranting increased input from the inpatient diabetes teams." (PMID 35095757, 2021). "Type 2 diabetes mellitus (T2DM) is a complex disease characterized by high glucose plasma levels due to insufficient insulin secretion or action or both affecting people of all age groups." (PMID 34641501, 2021). "It is imperative across all countries that patients with diabetes requiring insulin, especially children and adolescents, are well managed given the burden of the disease and its potential complications, as well as the additional burden during their education." (PMID 35095504, 2021). "In type 1 diabetes mellitus, the destruction of insulin-producing beta-pancreatic cells results in an inability to control blood glucose levels since insulin signals glucose uptake into cells." (PMID 34795665, 2021).
diabetes (continued). "Originally identified as a monogenic cause of permanent neonatal-onset DM, this syndrome (designated mutant INS-gene-induced diabetes of youth; MIDY) can also present in childhood or adolescence (maturity-onset diabetes of the young; MODY)." (PMID 34659132, 2021). "Diabetes and technologies supporting diabetes care, including glucose monitoring devices, software analyzing glucose data, and insulin delivering systems, would facilitate remote and structured disease management." (PMID 33769945, 2021). "They had better postoperative weight loss, were younger, and the duration of T2DM was shorter with less insulin requirement and less diabetes-related complications." (PMID 33151518, 2021). "The differentiation of human stem cells into insulin secreting beta‐like cells holds great promise to treat diabetes." (PMID 33145960, 2021). "The current paradigm of type 2 pre-diabetes/diabetes (T2D) maintains that glycemic control reflects the interplay between insulin production by beta-cells and the peripheral sensitivity/resistance to insulin." (PMID 34659123, 2021). "Diminished insulin clearance at baseline has been found to correlate with future development of diabetes." (PMID 34206745, 2021). "Lengthening the action time of basal insulin and restricting peaks of fast-acting insulin can be beneficial for individuals with diabetes." (PMID 34203830, 2021). "We were unable to take duration of insulin therapy into account, but we adjusted for diabetes duration." (PMID 33776906, 2021). "This literature review focused on the efficacy, benefits, and limitations of using Intranasal Insulin and its effect on the cognitive function of people with diabetes." (PMID 34540446, 2021). "In this situation, the adolescent with diabetes claims to have felt bewildered, as she cannot fathom that kind of comparison with regards to a therapeutic procedure (insulin injection) essential for her health." (PMID 33672506, 2021). "Our aim was to fractionate the cell populations produced by differentiation of human pluripotent stem cells into pancreatic islet-like clusters, in order to select the insulin-producing cells which are most active to normalize glycemia in diabetes models." (PMID 34025576, 2021). "This lipotoxicity has the potential to induce insulin resistance in muscle cells, and thus contribute to the pathophysiology of diabetes." (PMID 35002962, 2021). "Biological aging is broadly defined as the time-dependent loss of functionality and robustness, and is associated with increased rates of cancer, cardiovascular and neurodegenerative disease, diabetes or dysglycemia, insulin and anabolic resistance." (PMID 34063658, 2021). "The genomic test can be used for screening for diabetes autoantibodies remains drug or insulin dose." (PMID 34204428, 2021). "Our study was conducted to examine the effects of 3-week CR on glucose tolerance and fasting insulin concentrations in the late stage of diabetes." (PMID 33916828, 2021). "Sulfonylureas are the most popular second‐line treatment prescribed for type 2 diabetes mellitus, promoting insulin release via inhibition of pancreatic KATP channels." (PMID 33932103, 2021). "The Glucose Buddy Diabetes Tracker features support blood glucose, A1C, insulin, and prescription medication tracking while also requiring integration with Apple Health or other comparable fitness apps to track physical activities." (PMID 34463627, 2021). "In total 20 individuals with type 1 diabetes (7 females) were included in the study with a mean ± SD age of 35 ± 11 years, BMI 24.8 ± 2.8 kg/m2, HbA1c 54 ± 7 mmol/mol (7.1 ± 0.6%), diabetes duration 20 ± 11 years, total daily insulin dose 40 ± 14 IU." (PMID 34295305, 2021). "In the E-CABG registry, 54% of people with type 2 diabetes treated with non-insulin medications and 67% of those with insulin-treated diabetes had an HbA1c above 53 mmol/mol (7.0%) prior to cardiac surgery." (PMID 34404479, 2021).